PMS2 (PMS1 homolog 2, mismatch repair system component)
Diseases named in the same sentence as PMS2 in open-access papers (continued):
Sharing a sentence is not in itself a finding about the gene and the disease.
colorectal cancer (continued). "Microsatellite instability (MSI) is a key feature in colorectal carcinomas (CRCs), but its role in diagnosis and prognosis, particularly through immunohistochemical markers like MSH6 and PMS2, remains underexplored." (PMID 41907888, 2025). "For breast and colorectal cancers (n = 731), PVs were most frequent in CHEK2 excluding I157T (2.2%, 95% CI 1.4–3.5%), ATM (1.2%, 95% CI 0.6–2.4%), MLH1 (0.8%, 95% CI 0.3–1.9%), and PMS2 (0.7%, 95% CI 0.3–1.7%)." (PMID 36856935, 2023). "With the PMS2 and WRN results, a pathological connection can be found between the patient's jejunal cancer and colorectal cancer." (PMID 25018888, 2014). "We discuss predicted functions for the gene products of MLH1, PMS2 and EPHB4, all of which have an established importance for colorectal cancer." (PMID 21171995, 2010). "In our study, due to differences in the classification of cancer types and potential variations in ethnicity, PMS2 gene did not have the highest proportion in the non-CNS LS-related tumor group, which includes colorectal cancer." (PMID 41261115, 2025).
colorectal cancer (continued). "Gill suggested that inactivation of PMS2 may play an important, but limited, role in the development of sporadic MSI-H colorectal cancers." (PMID 28451866, 2018). "The three tumours that showed no staining of PMS2 by IHC were two colorectal cancers and one endometrial cancer." (PMID 24790682, 2014). "We also verified our predictions on a set of genes that play an important role in colorectal cancer (MLH1, PMS2, EPHB4 ) and could confirm more than 73% of them based on evidence in the literature." (PMID 21171995, 2010). "Of the two individuals who carried two DV in genes other than MUTYH, one was affected with colorectal cancer and carried a DV in CHEK2 and PALB2, while the second was not personally affected with cancer but did have a family history of breast and gastric cancer and carried DV in PMS2 and CDH1 genes." (PMID 29308099, 2018).
endometrial cancer (109 papers, 2010 to 2026). Primary or metastatic malignant neoplasm involving the endometrium (mucous membrane that lines the endometrial cavity). "Although PMS2 mutations have comparatively lower penetrance, carriers remain at increased lifetime risk for colorectal and endometrial cancers." (PMID 41416262, 2025). "The nuclear model was further validated in MSH6 and PMS2 in endometrial cancer, where loss of expression was significantly associated with longer CSS for both manual and DL scores." (PMID 39040241, 2024). "We report a case of a 47-year-old woman with history of papillary thyroid cancer whose diagnosis of melanoma led to cancer genetics evaluation revealing a pathogenic PMS2 variant and subsequent identification of endometrial cancer." (PMID 39188332, 2024). "Previous studies have indicated a notable discordance between IHC and molecular tests, especially in MSH6‐ and PMS2‐deficient endometrial carcinomas." (PMID 39132875, 2024). "Combined deficiencies in MLH1 and PMS2 account for approximately half of MMRd endometrial carcinomas, the majority of which are caused by promoter hypermethylation of the MLH1 gene, with about 10% of cases caused by somatically acquired mutations." (PMID 38539494, 2024). "MLH1/PMS2 loss due to MLH1 promoter hypermethylation (MLH1-PHM) is the most common cause of mismatch repair (MMR) deficiency in endometrial cancer (EC)." (PMID 37958361, 2023). "Although 10-20% of endometrial cancer patients had loss of MLH/PMS2 expression, very few had germline MLH1 or PMS2 mutations." (PMID 34048176, 2021). "In this study, we review the frequency of this IHC pattern among colorectal (CRCs) and endometrial cancers (ECs) in our files and present two CRCs showing loss of PMS2 and MSH6." (PMID 32664968, 2020). "In the Prospective Lynch Syndrome Database (PLSD) the risk for endometrial cancer at age 75 in PMS2 variant carriers was estimated at only 13%." (PMID 32854222, 2020). "We review the frequency of this MMRD IHC pattern among 108 colorectal (CRCs) and 35 endometrial cancers in our files with loss of expression of at least one protein, and present two CRCs showing loss of PMS2 and MSH6 protein expression (1.9% of CRCs)." (PMID 32664968, 2020). "All MS molecular approaches identified the E9 endometrial cancer sample as MSS while sole IHC testing showed a MSI/dMMR phenotype (with a loss of expression of the PMS2 protein)." (PMID 33009475, 2020). "PMS2 variants seem to confer a somewhat lower endometrial cancer risk than variants in the other three genes." (PMID 32854222, 2020).
endometrial cancer (continued). "PMS2 mutations carry a cancer risk of 15% to 20% for colon cancer and 12% to 15% for endometrial cancer compared with that of the general population." (PMID 29225998, 2016). "However, it is essential to note that the role of RRS for pathogenic PMS2 carriers requires further evaluation due to their relatively lower risk of endometrial cancer." (PMID 39768893, 2024). "However, the prevalence of mutations in MSH6 and PMS2 in endometrial cancer patients with LS has been reported to be 52–72% in recent studies, as determined using multigene panel tests." (PMID 35884469, 2022). "The patterns of increased familial cancers suggest that BRCA2 mutations could contribute to associations of ALL with breast and prostate cancers, and mismatch gene PMS2 mutations with rectal and endometrial cancers." (PMID 34117277, 2021). "Importantly, it is clinically feasible to assess these markers at diagnosis to tailor therapy since diagnostic assays for MLH1 and PMS2 loss are routinely implemented in clinic for colorectal and endometrial cancer patients." (PMID 34011995, 2021). "The expression of PMS2 mutation has been found to increase the risk of endometrial cancer and AXIN2 polymorphisms may activate the Wnt pathway associated with reproductive tract carcinomas." (PMID 32545766, 2020). "However, as one of the MMR genes, PMS2 mutation-induced LS-associated endometrial cancer (LSAEC) was rarely reported." (PMID 31860975, 2019). "His children are all of appropriate age for colonoscopy screenings and may require them more frequently (every 1–2 years), and his daughters could benefit from increased endometrial cancer surveillance if they are found to carry the PMS2 mutation." (PMID 29225998, 2016). "In addition, it is estimated that PMS2 carriers have a 15% lifetime risk of endometrial cancer (compared to up to 60% with other LS-associated MMR genes)." (PMID 26484312, 2015). "In low-grade endometrial carcinomas, clinically confined to the uterine body, MSI, based on the loss of function of MLH1/PMS2, increases the likelihood of myometrial infiltration." (PMID 41003120, 2025).
endometrial cancer (continued). "Three mosaic cases of endometrial cancer (Case # 839, # 905, and # 973) which were loss of MLH1 and PMS2 in MMR‐IHC was methylated both pMMR and dMMR portion." (PMID 35596629, 2022). "For isolated PMS2 loss, the prevalence of LS (47.6%) was very close to that reported in previous studies for CRC and endometrial carcinoma, varying from 35% to 45%16,49." (PMID 34545179, 2022). "One patient had an endometrial carcinoma treated with radiotherapy before surgery, the tumor was MSS with a loss of MLH1 and PMS2." (PMID 34545179, 2022).